PGR (progesterone receptor)
Diseases named in the same sentence as PGR in open-access papers (continued):
Sharing a sentence is not in itself a finding about the gene and the disease.
cancer (continued). "To inquiry genetic alterations of ESR1, ESR2, and PGR that may be associated with tumorigenesis, we analyzed these in pan-cancer involving a total of 10,189 patients." (PMID 34322374, 2021). "In addition, 112 ESR2 and 214 PGR nonsynonymous mutation sites were detected in different cancers, with the highest frequency mutations in R227H/C/L and R740Q/*." (PMID 34322374, 2021). "LumB cancers have high expression of the proliferation marker Ki67, which correlates with increased risk of developing distant metastases, and reduced expression of the progesterone receptor (PR), which shifts gene expression toward more tumorigenic genes." (PMID 32039208, 2019). "The results suggest that the PgR +331G/A polymorphism might be associated with an increased female reproductive cancer risk." (PMID 23349706, 2013). "We detected a mild association between PgR +331 G/A polymorphism with overall female cancer risk." (PMID 23349706, 2013). "However, ER(+)/PgR(−) cases tended to express higher levels of miRNAs associated with ER-positivity (miR-30a-5p, miR-29c-3p, miR-141-3p), whereas ER(−)/PgR(+) cancers showed elevated levels of miRNAs characteristic for double- and triple-negative tumors (miR-92a-3p, miR-424-5p)." (PMID 32825530, 2020). "However, it is possible that women who start to smoke as teenagers may have a higher risk of developing postmenopausal ER-/PgR- cancer." (PMID 24516791, 2014). "Thus, some subjects with particular characteristics who start smoking as teenagers may have a higher risk of developing postmenopausal ER-/PgR- cancer." (PMID 24516791, 2014). "With respect to this biological postulation, the +331G/A PgR may modulate cancer risk." (PMID 23349706, 2013). "Progesterone Receptor (PGR) and Ribosomal protein S6 kinase (RPS6KA1) were identified as two core targets in the cancer risk prognostic model." (PMID 40678730, 2025). "Interval cancers with DBT (vs DM) less frequently had favorable characteristics: estrogen receptor–positive or progesterone receptor–positive (72.3% vs 84.8%, respectively) and ERBB2-negative (79.2% vs 86.2%, respectively)." (PMID 40402477, 2025). "The hormone-receptor-positive (HR+) subtype encompasses cancer cells that express the estrogen receptor (ER) and progesterone receptor (PR), which stimulate cancer cell growth." (PMID 40006021, 2025). "Other independent factors associated with pCR included age at onset (OR 0.969; p = 0.027), progesterone receptor status (OR 2.028; p = 0.036), clinical T stage (p = 0.002), and overall cancer stage (p = 0.001)." (PMID 40427118, 2025). "We adjusted baseline comorbidities, cancer therapy, cancer staging and grade, and pathological status of estrogen receptor and progesterone receptor." (PMID 41127513, 2025). "Hormone receptor-positive (HR+) cancers include estrogen receptor (ER+) and progesterone receptor (PR+) cancers, and can be subdivided into luminal A and luminal B cancers." (PMID 39123362, 2024). "Hormone receptor-positive BC, the most common subtype, expresses estrogen receptor (ER) and/or progesterone receptor (PgR), and endocrine therapy largely plays a pivotal role in decreasing disease recurrence and cancer death." (PMID 38180699, 2024). "PD-L2 was expressed in 79.09% of the cancer samples, which exhibited a positive correlation with the progesterone receptor (PR) and the human epidermal growth factor receptor 2 (HER2)." (PMID 38983273, 2024). "For example, the GR, AR, Progesterone receptor (PGR), and ER boast 51, 25, 20, and 19 approved drugs (mainly anti-cancer), respectively." (PMID 39065726, 2024).
cancer (continued). "Recent studies in mice show a possible positive influence of progesterone receptor (PR) activating drugs on cancer cell growth." (PMID 36769131, 2023). "KLF2 expression levels were found to be reduced in advanced cancer stages and grades, while positively correlated with the expression of estrogen receptor (ER), progesterone receptor (PR), and tumor size in breast cancer." (PMID 37123417, 2023). "These targets, except PGR, were overexpressed in at least one cancer type, while most of these genes were predominantly downregulated in aging GTEx tissues." (PMID 37888486, 2023). "Kaplan–Meier Plotter showed that GPR176 mRNA expression was positively correlated with the relapse-free survival (RFS) of all cancer patients (p < 0.05) and the overall survival (OS) of PR (progesterone receptor)-positive cases (p < 0.05)." (PMID 37079213, 2023). "A lower PgR expression retains cancer cells in a “silent” mode during the HT within the first 5-years, after which they resume the replication phenomenon." (PMID 36817766, 2023). "Progesterone is an important naturally occurring sex hormone whose cellular effects are mediated by adsorption on the progesterone receptor and modulating hormone-responsive target genes in several cancer types." (PMID 38115900, 2023). "For example, this is the case for estrogen response genes (e.g., ESTROGEN_RESPONSE_EARLY) specifically enriched in BRCA, with ESR1 and PGR highly correlated with MAPT in this cancer type." (PMID 37730697, 2023). "On the other hand, the progesterone receptor is a favorable prognostic marker for multiple solid tumors, but its expression is reduced in malignant tumors." (PMID 37152960, 2023). "Despite the fact that most patients with EC exhibit decreased expression of progesterone receptors, there have only been a few mechanistic experiments targeting PGR and cancer cells." (PMID 37723477, 2023). "The protein of progesterone receptor (PR) is encoded by the progesterone receptor gene (PGR), which can modulate the immune response in different cancers." (PMID 37189448, 2023). "About invasive luminal cancers, we found a potential role of AR/PgR ratio > 0.96 in predicting the efficacy of first-line endocrine treatment in HR+ advanced BC." (PMID 36111296, 2022). "Tamoxifen, used in the treatment of ER/PgR‐positive cancers, is reduced by the CYP enzymes into its active metabolites N‐desmethyl‐tamoxifen, 4‐hydroxyl‐N‐desmethyl‐tamoxifen, and 4‐hydroxy‐tamoxifen." (PMID 35902379, 2022). "Various other NRs have been investigated as potential therapeutic targets in cancer, which include the glucocorticoid receptor (GR), progesterone receptor (PR), RARs, and RXRs." (PMID 35631448, 2022). "These innovations have increased the capacity to treat specific cancer profiles – oestrogen receptor-positive, progesterone receptor-positive and HER2-positive cancers." (PMID 35274583, 2022). "Approximately 70–80% of breast cancers are hormone-dependent; the majority are identified as estrogen receptor-positive (ER+) cancers which also express the progesterone receptor (ER+/PR+)." (PMID 36145265, 2022). "In clinical facilities across, these intrinsic subtypes of cancer are recognized in the presence of immune-histochemical molecules, like estrogen receptor (ER), progesterone receptor (PR), HER2 expression and Ki67 labelled index." (PMID 35304514, 2022). "For certain subtypes such as estrogen/progesterone receptor-positive cancers there has been an expanded use of molecular testing (such as Oncotype DX) on diagnostic core biopsies in recent years." (PMID 36290888, 2022). "Progesterone receptor (PR) has emerged as a potential therapeutic target due to its increasingly recognized role in cancer development and progression." (PMID 36180453, 2022). "Triple-negative breast cancer (TNBC) is a cancer where estrogen receptor (ER), progesterone receptor (PR), and human epidermal growth factor receptor 2 (HER-2) are all negative." (PMID 35664559, 2022).
cancer (continued). "70% of breast cancers involve Hormone-positive receptors that have a progesterone receptor (PR) or estrogen receptor (ER) on the cancer cell." (PMID 36091438, 2022). "Regarding the progesterone receptor status, more cancers were receptor positive (PgR+) in premenopausal than in peri- or postmenopausal women, and levels of PgR+ decreased with menopausal status." (PMID 36497561, 2022). "In vitro and in vivo experimental studies have likewise demonstrated suppression of cell proliferation and survival following treatment with E2 and P4 by ERβ and/or PGR-mediated anti-cancer activities." (PMID 36263327, 2022). "This group exhibited the highest value of progesterone receptor (PgR) expression; a balanced distribution of G2/G3 carcinomas (15/15), PAM50 subtypes (12 luminal-A, 17 luminal-B, 1 HER2-enriched); and HER2 groups (HLBC- = 12, HLBC-2N = 7, and HLBC-2E = 11)." (PMID 36038884, 2022). "During tumorigenesis, ERα expression was noted in all types of precursor lesions and persisted in cancer, whereas PgR expression was lost very early." (PMID 34638241, 2021). "Approximately 50–70% of all basal-like cancer patients lack the expression of estrogen receptor (ER), progesterone receptor (PR), and HER2, and therefore are clinically described as being triple negative." (PMID 33477536, 2021). "The lack of typical receptors such as human epidermal growth factor receptor 2 (HER2), progesterone receptor (PR) and estrogen receptor (ER) on this cancer subtype precludes usage of currently available targeted therapeutic agents." (PMID 34026654, 2021). "Regarding breast cancer subtypes, it was most abundant in those with TNBC, while lowest in ER+ (estrogen receptor) and ER/PR+ (progesterone receptor) cancer." (PMID 34123844, 2021). "Among these subsets, luminal cancers are characterized by estrogen (ER) +/− progesterone receptor (PR) expression." (PMID 34885109, 2021). "Our results revealed genetic alterations in ESR1, ESR2, and PGR in multiple cancer types, including amplification, fusion, deep deletion, missense mutation, and truncating mutation." (PMID 34322374, 2021). "To assess the relevance of ESR1, ESR2, and PGR with immune system that plays critical roles in cancer progression, we first compared their co-expression with the abundance of immunomodulators." (PMID 34322374, 2021). "HR-positive subtype of breast cancer is categorized by slow-growing cancer cells that are fueled by overexpressed hormone estrogen receptor (ER) and progesterone receptor (PR)." (PMID 33670524, 2021). "Various processes involved in the down-regulation of PgR have distinct consequences on the biology of cancer cells." (PMID 34638241, 2021). "To explore the expression of ESR1, ESR2 and PGR in pan-cancer, we analyzed their mRNA levels via GEPIA2." (PMID 34322374, 2021). "To investigate the distribution of ESR1, ESR2, and PGR isoforms in pan-cancer, we compared their expression levels via GEPIA2." (PMID 34322374, 2021). "Together, the potential roles of ESR1, ESR2 and PGR in cancer are likely in an immune system-dependent manner." (PMID 34322374, 2021). "According to the guidelines of the American Society of Clinical Oncology (ASCO) 2010, the positive status of ER or PgR, which is defined as the presence of at least 1% stained cancer nuclei of ER or PgR, is an indication for subsequent endocrine treatment." (PMID 34638491, 2021). "Generally, the results of this study indicated that ESR1, ESR2, and PGR can be regarded as predictive and prognostic biomarkers across different cancer types." (PMID 34322374, 2021). "Luminal A are cancers with ER+, PR+ and Ki67 < 20% and ER+, PgR+/− and Ki67 < 14%, and the best prognosis." (PMID 34202321, 2021).
cancer (continued). "The diagnosis of cancer preoperatively allows evaluation of prognostic factors including estrogen and progesterone receptor status of the tumor, Her2 status, grade, and type of cancer." (PMID 34755489, 2021). "Well-known parameters such as cancer type, grade, subtype, estrogen receptor, progesterone receptor, human epidermal growth factor receptor 2, Ki-67, and MDR-1/P-gP have been used for selecting chemotherapy regimens." (PMID 34691411, 2021). "The understanding of PgR significance in BC is further complicated by the coexistence of its isoforms, as phosphorylated PgR-A is a more potent driver of cancer stem cell expansion, whereas PgR-B is involved in BC cells proliferation." (PMID 34638241, 2021). "To investigate the potential roles of ESR1, ESR2, and PGR in prognosis, we analyzed the correlation of their expression with pan-cancer survival." (PMID 34322374, 2021). "If the cancer is estrogen receptor (ER)- or progesterone receptor (PR)-positive, hormonal therapy is the preferred treatment, with or without chemotherapy." (PMID 32271809, 2020). "Breast cancer is a heterogeneous spectrum of mammary gland-derived malignant tumors that can be subtyped by molecular profile in terms of standard-estrogen receptor (ER), progesterone receptor (PR), and human epidermal growth factor receptor 2 (HER2)." (PMID 32927665, 2020). "We are also examining the effect of PARPi on cancer cells from advanced and early-stage breast cancers with the different status of ER/PR (progesterone receptor) and HER2 receptors." (PMID 32235451, 2020). "ER(−)/PgR(+) tumors were characterized by a higher grade and a higher Ki-67 index than ER(+)/PgR(−) cancers in the NanoString cohort, whereas in the TCGA cohort, ER(+)/PgR(−) patients presented more frequently with positive lymph nodes." (PMID 32825530, 2020). "Recently, the antiprogestin activity of selective progesterone receptor (PR) modulator mifepristone (MF) has proven unsuccessful as a potential anti-cancer agent in various clinical trials." (PMID 33158280, 2020). "BRCA1 mutation breast cancers are predominantly triple negative/basal-like, which means these cancers lack the expression of human epidermal growth factor receptor 2, estrogen receptor (ER), and progesterone receptor (PR)." (PMID 33299637, 2020). "Triple-negative breast cancer (TNBC) cells are cancer cells that lack estrogen receptor (ER), progesterone receptor (PR), and human epidermal growth factor receptor 2 (HER2) expression." (PMID 33114669, 2020). "Clinical features such as the age at diagnosis, cancer status, cancer subtype, oestrogen and progesterone receptor status (designated by ER and PR status respectively, in the following paragraphs) are available for all patients with no missing value." (PMID 32197576, 2020). "A significantly higher proportion of cases expressed PgR and had a Ki67 ≤ 20% among screen-detected cancers compared with symptomatic tumors (78.1% v 68%, P = .04; and 57.1% v 44.1%, P = .02, respectively)." (PMID 32678710, 2020). "This shows a stronger interaction of the extract with the MMP9 protease enzyme than either with the estrogen receptor or progesterone receptor which is commonly present in luminal A cancer type." (PMID 33066411, 2020). "In 2011 a new occult carcinoma was found in her right axilla, however the specimen was estrogen receptor (ER) and progesterone receptor (PgR) positive." (PMID 32206145, 2020). "On the contrary, ER(+)/PgR(−) tumors show a higher expression of miRNAs typical for double-positive luminal carcinomas." (PMID 32825530, 2020). "The patient underwent left mastectomy and axillary lymph node (LN) dissection, and analysis of the specimen revealed that the cancer was estrogen receptor (ER)- positive, progesterone receptor (PR)- positive, and HER2-negative." (PMID 31640606, 2019). "Cancers that are positive for estrogen receptor (ER+) and/or progesterone receptor (PR+) in IHC are classified as luminal." (PMID 30382472, 2019).
cancer (continued). "We recommend that pathologists discuss with clinicians, or re-test and re-evaluate the ER/PgR expression, particularly in low-grade carcinoma and with a high staining proportion of PgR in the ER−/PgR+ phenotype." (PMID 30066060, 2019). "Herein, we re-evaluated all the ER−/PgR+ carcinoma cases which we have encountered according to the standard IHC methods." (PMID 30066060, 2019). "We recommend that pathologists discuss with clinicians, or re-test and re-evaluate ER/PgR expression, particularly in low-grade carcinoma and with a high staining proportion of PgR in the ER−/PgR+ phenotype." (PMID 30066060, 2019). "In our study, most of the initially evaluated ER−/PgR+ cases were ER+/PgR+ low-grade carcinomas after re-evaluation by IHC." (PMID 30066060, 2019). "Here, we re-evaluated ER-negative/PgR-positive (ER−/PgR+) carcinoma cases by immunohistochemical staining (IHC)." (PMID 30066060, 2019). "Despite several reports stating that AR expression is acquired in HER2/ESR1/PGR triple-negative cancers, here we show that a low percentage of these cancers express AR (~20%)." (PMID 30279965, 2018). "Parity was also related to the observed positive association between progesterone receptor and Ki-67 indices in cancer tissue, implying progesterone receptor–dependent cell proliferation." (PMID 30254198, 2018). "cSBL significantly suppressed the cell growth of six cancer cell lines representing a variety of phenotypes in ERα, PgR, and HER2 through the induction of apoptosis." (PMID 30347895, 2018). "Carcinomas were evaluated by immunohistochemistry for estrogen receptor, progesterone receptor, and the cell proliferation marker Ki-67." (PMID 30254198, 2018). "This is supported by the observation that HER2 absent (0+) tumors show highest shares of LMA ER + PgR+ and of HMA ER-PgR- cancers." (PMID 28356061, 2017). "As orphan nuclear receptors ERRα, ERRβ, ERRγ and PgR are significantly involved in increased cancer cell proliferation, we studied their possible contribution in anti-cancerous effects of artemisinin." (PMID 29246124, 2017). "KLK4 expression in cancer cell lines, has been shown to be regulated by activation of both androgen receptor (AR) and progesterone receptor (PR)." (PMID 29249975, 2017). "In that respect, it is similar to more familiar cancer targets such as oestrogen receptor, androgen receptor and progesterone receptor." (PMID 28481952, 2017). "Molecular alterations are known to affect cancer occurrence and metastasis, which has led to the development of hormonal therapy that targets the estrogen receptor (ER), progesterone receptor (PR), or human epidermal growth factor type 2 (HER-2)." (PMID 29041905, 2017). "A plausible interpretation of our results is that the inherent mitotic activity of ER + PgR+ cancers is low and HER2 overexpression can act as a promitotic factor in some of these tumors showing the intermediate level of mitotic activity." (PMID 28356061, 2017). "Secondary variables: age, personal history of breast surgery, personal history of any cancer/BC, premenopause, postmenopause, grade, estrogen receptor, progesterone receptor, c-erbB2, TNM stage, multicentricity/multifocality, diagnosis and treatment." (PMID 28341842, 2017). "ER/PgR‐positive cancer, defined as luminal A or B, is amenable to hormonal therapies such as tamoxifen or aromatase inhibitors and associated with good prognosis." (PMID 28781955, 2017). "On the other hand, clusters of low mitotic activity (LMA) were present only in ER positive cancers (both in PgR+ and PgR- cancers)." (PMID 28356061, 2017). "PgR is an ER-regulated protein, and the presence of PgR in the cancer cells has long been considered as a result of activated ER." (PMID 27722840, 2016). "It is stated that 21 % of the ER-negative cancers were PgR-positive, indicating that the PgR technique used resulted in many false positive PgR classifications." (PMID 27722840, 2016).